TM4SF5 (transmembrane 4 L six family member 5)
Diseases named in the same sentence as TM4SF5 in open-access papers (continued):
Sharing a sentence is not in itself a finding about the gene and the disease.
cancer (19 papers, 2008 to 2025). A tumor composed of atypical neoplastic, often pleomorphic cells that invade other tissues. "TM4SF5 expression results in acquired cancer stem cell properties via a physical association with CD4417." (PMID 31501417, 2019). "Co-cultures exhibited TM4SF5-positive or cancer-associated fibroblasts at the outward edges of TM4SF5-null cell clusters." (PMID 29137358, 2017). "The researchers found that TM4SF5 helps cancer cells absorb ALB through a process called macropinocytosis, which supports energy production and cell movement." (PMID 40186033, 2025). "As compared to others, this review aimed to present a focused insight and update on the biological roles of TM4SF1, TM4SF4, and TM4SF5 in the progression, metastasis, and chemoresistance of various cancers." (PMID 36678607, 2023). "Accumulating evidence has demonstrated, among six TM4SF members, the regulatory roles of transmembrane 4 L6 domain family members, particularly TM4SF1, TM4SF4, and TM4SF5, in cancer angiogenesis, progression, and chemoresistance." (PMID 36678607, 2023). "In this study, we evaluated the effects of chimeric Ab27 using cancer cells expressing endogenous TM4SF5 or stably overexpressing TM4SF5 in vivo and in vitro." (PMID 35211652, 2022). "TM4SF5 expression in cancer cells downregulated stimulatory ligands and receptors for NK cell cytotoxicity, including SLAMF6, SLAMF7, MICA/B, and others." (PMID 34921636, 2021). "Suppression or inhibition of TM4SF5 in target hepatocytes (cancer cells) increased the mRNA levels of stimulatory ligands in hepatocytes and cognate receptors in NK cells and also led to enhanced NK cell surveillance." (PMID 34921636, 2021). "In this study, the roles of TM4SF5 in the development of precancerous and cancerous phenotypes in genetically engineered or chemically treated animals were explored in regard to TM4SF5-dependent signaling and crosstalk between cancer cells and immune cells." (PMID 34921636, 2021). "Correspondingly, certain lung cell lines from the Cancer Cell Line Encyclopedia (CCLE) that highly express TM4SF5 exhibited a positive correlation with ESRP1/2 expression and negative correlation with ZEB2 expression." (PMID 31501417, 2019). "The angiogenic and vasculogenic transformation mechanisms of TM4SF5-positive cancer cells need further exploration." (PMID 29137358, 2017). "Here, TM4SF5-positive cancer cells expressed VE-cadherin and exhibited elongations to form networks, as if they were endothelial cells." (PMID 29137358, 2017). "TM4SF1 and TM4SF5 affect migratory mechanisms crucial to cancer invasion and metastasis, making them as crucial targets for cancer therapy." (PMID 25344917, 2014). "Monoclonal antibodies specific to an epitope of human TM4SF5 (hTM4SF5R2-3) can recognize native mouse TM4SF5 and induce functional effects on mouse cancer cells." (PMID 22427965, 2012). "Like TM4SF1, the expression profile of TM4SF5 has been studied and highly expressed in many cancers, such as pancreatic, gastric, colon, liver, papilla vateri, soft tissue, non-endocrine lung, and adrenocorticotropic hormone (ACTH)-negative bronchial carcinoid." (PMID 36678607, 2023). "Hence, TM4SF1, TM4SF4, and TM4SF5 are promising therapeutic targets for different cancer types preclinically and deserve further investigation." (PMID 36678607, 2023). "To determine whether Ab27 specifically recognizes endogenous TM4SF5 on the cancer cell surface, we performed flow cytometry of several types of cancer cells transiently transfected with TM4SF5-specific or negative control small interfering RNA (siRNA)." (PMID 35211652, 2022). "Because C57BL/6-TgTM4SF5 mice exhibited nonalcoholic steatohepatitis (NASH)-associated fibrotic livers, we determined whether TM4SF5 overexpression in a disease-susceptible mouse strain (i.e., FVB/N) caused an enhanced malignant cancer phenotype." (PMID 34921636, 2021).
cancer (continued). "Therefore, CPPs that disrupt the binding between TM4SF5 and c-Src can be therapeutically important for the treatment of TM4SF5-positive cancers." (PMID 34335982, 2021). "Additionally, we found that TM4SF5 expression levels in the target cancer cells showed an inverse relationship with the stimulatory ligand levels for NK cell cytotoxicity (left and middle)." (PMID 34921636, 2021). "TM4SF5 is overexpressed in different cancer types, including liver cancer." (PMID 31956272, 2020). "Such TM4SF5-dependent phenotypes in in vivo-like 3D gel systems could be promising platforms to explore the mechanistic aspects of TM4SF5-dependent cancer metastasis and to screen for anti-metastatic reagents." (PMID 29137358, 2017). "Therefore, it is likely that the humanized anti-TM4SF5 antibody increases cell-cell interactions and thereby reduces the migration capability in TM4SF5-expressing cancer cells." (PMID 27816969, 2016). "Studies in that cancer suggested that TM4SF5 could enhance p27Kip1 expression and phosphorylation and lead to epithelial-mesenchymal transition (EMT) to mediate tumorigenesis, metastasis and gefitinib resistance." (PMID 26709920, 2015). "Previously, we reported the efficacy of anti-cancer peptide vaccine targeting TM4SF5." (PMID 25268742, 2014). "TM4SF5 is involved in cell processes and may help cancer cells take up ALB from their surroundings." (PMID 40186033, 2025). "Additionally, TM4SF5 may also induce chemoresistance and cancer fibrosis by interacting with integrins α2, α5, β1, and EGFR." (PMID 36678607, 2023). "Studies have reported that TM4SF5 is highly expressed in up to 80% of CRC cells, making it a promising target for cancer-specific interventions." (PMID 39273182, 2024). "TM4SF5 is involved in metastasis via direct activation of FAK, promoting EMT and gefitinib-resistance of cancer cells." (PMID 29254164, 2017). "TM4SF5 is highly expressed in many tumors and scarcely found in normal cells, indicating the potential applicability of this approach to a variety of cancer types beyond CRC." (PMID 39273182, 2024). "Also, TM4SF1 is defined as a cancer stem cell marker, and TM4SF1 and TM4SF5 are reported to be involved in epithelial-to-mesenchymal transition, which is also associated with stemness properties." (PMID 25344917, 2014). "Thus, crosstalks between TM4SF5 and other membrane receptors, such as integrins and growth factor receptors, are thus likely to play a role in regulating EMT to mediate chemoresistance and cancer fibrosis." (PMID 36678607, 2023). "While acquiring these functions, TM4SF5-positive cancer cells may remodel environments to be more favorable for their metastasis than TM4SF5-negative cells." (PMID 29137358, 2017).
infection (1 paper, 2025). The state of being infected such as from the introduction of a foreign agent such as serum, vaccine, antigenic substance or organism. "Since cross-talks between cancerous hepatocytes and NK cells may indirectly or directly (via trogocytosis) affect TM4SF5 expression and location on NK cells, we first engineered NK92 cells expressing empty vector or ectopic TM4SF5-HA via lentiviral infection." (PMID 39828766, 2025).
TM4SF5 also shares sentences with these, for which no sentence is quoted: fibrosis (2 papers); gastric cancer (2); Abdominal obesity (1); alcoholic fatty liver disease (1); breast carcinoma (1); cholangiocarcinoma (1); liver (1); metabolic disorders (1); multiple myeloma (1); non-small cell lung carcinoma (1); portal hypertension (1).